IL18 (interleukin 18)
Diseases named in the same sentence as IL18 in open-access papers (continued):
Sharing a sentence is not in itself a finding about the gene and the disease.
infection (continued). "Under the low MOI conditions the presence of 30 mM KCl in the infection mediuminhibited the secretion of IL-1β and IL-18 from macrophages infected withYp-YopJKIM, suggesting an important role for K+efflux in caspase-1 activation." (PMID 21533069, 2011). "All IL-18−/− mice also succumbed to infection but mice died earlier than WT controls after DENV-2 infection (p = 0.0237)." (PMID 22206036, 2011). "IFN-γ expression was greatly increased after infection of mice and its production was preceded by increase in IL-12 and IL-18 levels." (PMID 22206036, 2011). "At 6.5 h post-infection, the supernatants of wild-type macrophages infected with F. novicida contained significantly increased levels of IL-18 compared to infected TLR2−/− macrophages." (PMID 21698237, 2011). "Optimal IFN-γ production in various infections models in mice is controlled by cytokines, especially IL-12 and IL-18." (PMID 22206036, 2011). "To further test the role of TLR2 in inflammasome-dependent responses, we measured the levels of IL-1β and IL-18 in macrophage supernatants following infection with F. novicida." (PMID 21698237, 2011). "The highest score upon analysis of the IL-12 and IL-18 modulated genes was given to the network that listed Gene Expression, Infection Mechanism, RNA Post-Transcriptional Modification as associated functions (score: 50)." (PMID 21949811, 2011). "A great number of publications have documented the role of IL-18 and IL-1β during infections with a variety of pathogens." (PMID 22241982, 2011). "We also chose CCL19, c-FLIP (CFLAR), EBI3, and IL-18, which appeared differently modulated following the four infections, in order to verify such dissimilarity." (PMID 21436989, 2011). "Both Ca-074-Me and z-FA-fmk almost completely abolished IL-18 secretion in response to influenza A virus (Udorn/72) infection." (PMID 21589892, 2011). "First, we examined the daily regulation of cytokines mobilized following insult to the host by injury or infection, including TNFά, IL-1β, IL-6 and IL-18." (PMID 21194436, 2010). "In conclusion, IL-1β/IL-18 processing during infection is a complex process in which the inflammasomes are only one of several activation mechanisms." (PMID 20195505, 2010). "Among interleukins, IL-18 and the IL-18 binding protein played a prominent role early in the course of infection, while later IL-15 became increasingly up regulated." (PMID 19583830, 2009). "Although IL-18 and IL-1β production in response to LPS and infection varied markedly between donors; Mφ1 of all donors produced both IL-18 and IL-1β in response to these stimulations." (PMID 20027291, 2009). "To determine whether IL-18 directly contributes to ILC2s expansion during CR infection, we injected CR-infected mice with IL-18 binding protein (IL-18 BP) intraperitoneally (IP) on 2 and 3 dpi." (PMID 40591723, 2025). "Here, GSDME deficiency modestly reduced levels of IL-1β but not IL-18 in the airways following HKx31 infection, potentially due to differential regulation of the expression of these cytokines in vivo." (PMID 40481027, 2025). "Additionally, IL-18 stimulates the production of interferon-γ by natural killer cells and T cells to impact the occurrence of postoperative infection." (PMID 41376789, 2025). "The protein expression of two proteins (IL-17C and IL-18) was significantly decreased and the protein expression of two proteins (TGF-α and LIF) was significantly increased in caspase-4-deficient cells compared to Cas9 cells following HK1651 infection." (PMID 40137780, 2025). "We have previously shown that infection with SARS-CoV-2 P21 causes increased production of a range of pro-inflammatory cytokines in the lungs of infected WT animals at multiple time points post-infection, including IL-1β, IL-18, IL-6, TNF, IFN-γ and others." (PMID 40016339, 2025).
infection (continued). "The elevated IL-18 levels in the non-abdominal sepsis group suggest its involvement in the more severe inflammatory response associated with another type of infection than abdominal causes." (PMID 40510342, 2025). "N. caninum infection induces the release of IL-1β and IL-18, cleaved caspase-1, and cell death in mouse bone marrow-derived macrophages, while infection of mice deficient in NLRP3, ASC, and caspase-1/11 leads to a decrease in IL-18 production and an increase in IFN-γ in the serum." (PMID 41357231, 2025). "Interestingly, however, IL-18 and IL-23 were increased in the lungs of these animals upon infection." (PMID 40016339, 2025). "In vitro infection of PBMC with EBV induced IL-18 secretion by monocytes, and blocking this cytokine reduced MAIT cell activation suggesting that IL-18 may be important in MAIT cell phenotype in this disease." (PMID 40519914, 2025). "We report that IL-18-stimulated cytotoxic NK cells limit endogenous thymic regeneration, a critical process that ensures the restoration of immune competence after acute insults such as stress, infection, chemotherapy and radiation." (PMID 40935830, 2025). "In addition to memory response to infection, the simultaneous stimulation of NK cells with IL-12, IL-15, and IL-18 can lead to the generation of cytokine-induced memory-like (CIML) NK cells." (PMID 39066359, 2024). "Moreover, the 11 cytokines (i.e., SDF-1, SCYB16, sCD30, IL-11, IL-18, IL-8, IFN-γ, TNF-α, sTNF-R2, M-CSF, and I-309) were associated with the infection, mortality, disease progression and recovery, and long-term hospitalization." (PMID 38476443, 2024). "Previous work has shown that the placental trophoblast constitutively secretes the inflammasome cytokines as IL-1β and IL-18, and the infection with L. monocytogenes can also induce more activation of this pathway, leading to resistance against the bacteria infection." (PMID 38771057, 2024). "Similarly, Il-18 and Tnf-α showed significant upregulation after 3, 6, and 12 h of infection (p < 0.05), and Il-1β showed significant upregulation after 3 h (MOI = 1:10 and 1:1) and 6 h (MOI = 1:1) of infection (p < 0.05)." (PMID 38927100, 2024). "Notably, the level of IL-18 activation in vivo is positively correlated with the severity of infection and mortality." (PMID 38419084, 2024). "Similarly to the liver, infection with L. europaeus/GI.1 and GI.2 drastically reduced the expression level of IL-18 in the kidneys by a 27.5-fold and 3.3-fold reduction." (PMID 39273479, 2024). "Additionally, the protein expression levels of IL-18 and IL-1β in the cell supernatant increased significantly during infection, but decreased after NAR intervention in a dose-dependent manner." (PMID 38256101, 2024). "Moreover, the suppression of proinflammatory cytokines like IL1β and IL18 enables M. tb to evade immune detection and reduces the recruitment of immune cells to the infection site." (PMID 39125766, 2024). "Given the specificity of the IL-18 response, we next examined IL-18 receptor (IL-18R) expression to begin to understand why IFN-γ production is strongly impaired in splenic CD4+ T cells in Il18-deficient mice at day 8 post-infection." (PMID 39446964, 2024). "Interestingly, we observed the downregulation of genes such as Tnf-α, Il18, Mx1, Rig1, Pkr, Stat1, Stat2 and Irf9, which appear to be hallmarks of hRSV persistence in contrast to the acute infection." (PMID 39296294, 2024). "Mediating a similar outcome, Nlrp6 (the most downregulated innate gene at 6hrs post-infection; −30.2 fold) acts as a cytosolic sensor in macrophages and mediates the secretion of pro-inflammatory cytokines IL-18, IL-1β and TNF in response to ligand stimulation." (PMID 39344634, 2024). "To conclude, TOXO seropositivity (which mirrors past infection and current latency) was linked to increased circulating IL-18 and NSE levels, irrespective of diagnostic status." (PMID 38438515, 2024).
infection (continued). "One arm of the caspase-1 response mediates IL-18 release to impact T cell cytokine production and pathogen control, while other arms stimulate signaling (including through IL-1RAP), to mediate cellular recruitment to the site of infection." (PMID 39446964, 2024). "As an inflammasome sensor, NLRP12 initiates pyroptosis in response to infections by Yersinia pestis, Plasmodium chabaudi, and Toxoplasma gondii, which results in the secretion of IL-1β and IL-18 and a reduction in the pathogen burden." (PMID 39119293, 2024). "Ferritin, an ARP, is increased in many inflammatory states, and it may serve as a biomarker for CRS, HLH in hematologic disorders, but when used as a predictor of infection, ferritin is affected by a variety of factors including IL-6, IL-10, IL-18, and IFNγ." (PMID 39559703, 2024). "Additionally, the IL-18 level decreased most significantly in the Wh3Δmic1 infection group, and IL-1β also decreased to a certain extent." (PMID 39614314, 2024). "In WT mice, M84stop MCMV induced higher IL-18 serum levels than WT MCMV at 1.5 days post-infection." (PMID 38278864, 2024). "Inflammatory caspases (caspase-1, caspase-4, and caspase-5 in humans, and caspase-11 in mice) play key roles in the innate immune response against pathogen infection and regulate the production of the pro-inflammatory cytokines: interleukin 1 beta (IL-1β) and IL-18, leading to pyroptosis." (PMID 39625520, 2024). "To test this hypothesis, we performed a rescue experiment, where we administered recombinant IL-18 (rIL-18) at 10μg/kg or PBS to Cx3cr1+Casp1 deficient mice at 1 hour post-infection and on days 1, 3, 5, and 7 post-infection." (PMID 39446964, 2024). "In this context, reduced IL-18 production, due to rs1834481-G allele presence, may result in insufficient control of SARS-CoV-2 replication at the early stage of infection which could then lead to viral persistence." (PMID 37766191, 2023). "After infection, IL-18 and IL-34 geneexpression was measured to assess epithelial cell immune responses, and lactatedehydrogenase (LDH) activity was measured as an indicator of cell damage.Microscopy determined C. albicans morphology and penetration offungal cells through the keratinocyte monolayer." (PMID 37466528, 2023). "Therefore, we measured the expression mRNA levels of interleukin (Il)1b and Il18, which are induced by pyroptosis activation, in BMDMs during infection." (PMID 37457695, 2023). "Additionally, mRNA levels of pyroptosis-related genes (NLRP3, ASC, caspase-1, GSDMD, IL-18, and IL-1β) in the kidneys with W24Δhcp1 infection are considerably lower than in those with WT W24 infection." (PMID 36977062, 2023). "Moreover, Gasdermin D-deficient mice were susceptible to intraperitoneal bacterial infection, with serious damage to the spleen and reduced secretion of cytokines IL-1β and IL-18 during in vivo infection." (PMID 36761775, 2023). "In addition, the importance of the IL-18 response in the infection against the dengue virus has been demonstrated, dependent on IL-18 and the production of IFN-γ." (PMID 38140192, 2023). "Our data show that NOD1 is an important regulator of bioactive IL-18 production by epithelial cells in response to the infection and, moreover, that this NLR plays a protective role in tissue homoeostasis through its control of cell proliferation and apoptosis." (PMID 37365163, 2023). "Similar levels of cell death and interleukin 18 (IL-18) release were observed in WT and IRF1-deficient BMDMs in response to infection with S. Typhimurium and P. aeruginosa, suggesting that IRF1 is dispensable for cell death and IL-18 release under these conditions." (PMID 37557956, 2023). "However, the secretion of IL-18 induced by infection with all the strains was significantly suppressed in the NLRP3- or ASC-deficient macrophages." (PMID 37910490, 2023).
infection (continued). "Downstream of IL22–STAT3 activation is an IL18–IFNγ cascade, which might contribute to host defense against infections such as by adherent‐invasive E. coli." (PMID 36573340, 2023). "Furthermore, we show that inflammatory cytokines IL-12 and IL-18, induced by infection, are able to mediate functional and transcriptional changes in NK cells." (PMID 37828009, 2023). "Two key inducers of IFN-γ, IL-12 and IL-18, are important in primary immune responses to infection." (PMID 37325809, 2023). "Delta and Omicron infection only marginally altered mRNA expression of IL-1β (Delta vs Mock: p = 0.6114; Omicron vs Mock: p = 0.7534), IL-6 (p = 0.1910; p = 0.2619), IL-18 (p = 0.7755; p = 0.6092), TNF-α (p = 0.9080; p = 0.9405) and IFN-α (p = 0.0612; p = 0.2138)." (PMID 36883057, 2023). "This study further extended the previous work to show that mice lacking NLRP6, (an NLR known to induce IL-18 in the gut) were more susceptible to infection and had decreased levels of IL-18." (PMID 37325809, 2023). "Furthermore, it has been shown that IL-18 is necessary for the induction of streptococcal toxic shock-like syndrome during infection with the virulent serotype 2 S. suis strain SC-19." (PMID 38276150, 2023). "This hypothesis could explain IL-5, IL-1, IL-6, and IL-18 increased expression in the spleen after 2 weeks of infection following the upregulation in the intestine." (PMID 36187827, 2022). "Thus, the combination of IL-12, IL-18, and IFN-γ as well as inflammasome activation seem to be associated with a protective mechanism against infection." (PMID 36211380, 2022). "IL-1β and IL-18 are interleukins belonging to the IL-1 family and are produced as a response to cellular insults that range from infection, such as the classically described LPS-induced inflammasome activation, to metabolic imbalances resulting in ionic fluxes through cell membrane." (PMID 36361818, 2022). "IEC IL-18 is constitutive and links innate and adaptive immunity during infection." (PMID 35804396, 2022). "The studies prompted us to investigate the secretion of IL-1β and IL-18 after SEZ infection." (PMID 36311722, 2022). "Furthermore, NAIP-/- and NLRC4-/- THP-1s treated with MCC950 secreted negligible levels of IL-1α, IL-1β, and IL-18, similar to those observed during ΔsipB Stm infection." (PMID 35073381, 2022). "The mechanisms of Th1 responses to microbes may be blunted by the action of IL-18 BP thus reducing autoimmune responses to an infection." (PMID 36032110, 2022). "Our data clearly demonstrated that PE_PGRS19 caused macrophage pyroptosis leading to the release of pro-inflammatory cytokines, and the pretreatment of macrophages with the pyroptosis inhibitor NSA blocked the increased transcript levels of il-6, il-1β, and il-18 induced by Ms_PE_PGRS19 infection." (PMID 36557726, 2022). "Additionally, numerous studies have shown that the NLRP3 inflammasome is involved in cellular inflammatory responses and helps to recognize pathogen infection, thereby promoting the maturation of IL-1β and IL-18 in macrophages." (PMID 36430657, 2022). "Although the increased proportion of macrophages did not depend on GSDMD in both spleen and peritoneal lavage fluid (PLF), deficiency of GSDMD caused the minor release of the pro-inflammatory cytokines interleukin-1β (IL-1β) and interleukin-18 (IL-18) during the infection in vivo." (PMID 36311722, 2022). "Moreover, during infection, there is an increase in proinflammatory cytokines (interleukin (IL)-1α, IL-1β, IL-6, IL-8, IL-18, tumor necrosis factor (TNF)-α, IFN-γ, leading to a disbalance in immune surveillance mechanisms and changes in the tissue environment." (PMID 36294658, 2022). "In contrast, by flow cytometry and immunofluorescence analyses of fresh “untouched” crypt samples for stem cells and TA cells, we found that loss of Il-22, epithelial Stat3, or Il-18 in mice indeed cause a reduction of Lgr5+ and Ki67+ crypts at the steady state and during AIEC infection." (PMID 35169117, 2022).
infection (continued). "To study the effects of SubAB on inflammasome activation, we first investigated whether SubAB affects IL-1β and IL-18 production during infection of macrophages with STEC O113:H21." (PMID 35345462, 2022). "This suggests that basophil IL-18 signaling may be important for controlling the early inflammatory response to infection and promoting increased MC influx into the intestine later during infection." (PMID 35985797, 2022). "Thus, LSDV Atyrau-5BJN(IL18) demonstrated satisfactory immunogenicity and was able to protect cattle from infection with the virulent LSDV Atyrau/KZ." (PMID 36298570, 2022). "Furthermore, more virulent strains of HSV-1 cause more severe corneal pathology that is associated with increased IL-1β and IL-18 levels, and IL-18 contributes to HSV-2 pathology in a genital model of infection." (PMID 35038917, 2022). "IL-18 is indeed an inducer of IFNγ production, and it activates T cells and NK cells in synergy with IL-12; thus, its release in response to infection with attenuated strains might promote T cell responses." (PMID 35215216, 2022). "Our data show that recognition of T3SS-expressing P. aeruginosa strains by the caspase-1 dependent canonical inflammasome leads to pro-inflammatory responses, manifested by increases in caspase-1-activation, IL-1β, and IL-18 cytokine production, and leukocyte migration to the site of infection." (PMID 35277504, 2022). "Additionally, rJS/7/05/Ch induced higher levels of IL-18 than rMukteswar in the thymus throughout the infection." (PMID 35711809, 2022). "Moreover, infection progression led to a gradual increase in IL-18 production, whereas higher levels of IL-12 production were observed during the early phases of infection." (PMID 36405684, 2022). "In this study, SFTSV infection induced processing of pro-caspase-1 and subsequent maturation and secretion of IL-1β/IL-18 were significantly suppressed in human PBMCs when NLRP3 gene was knocked down by specific shRNA or inhibited by a specific inhibitor, glibenclamide." (PMID 35173184, 2022). "Interestingly, in caspase-1-knockdown cells IL-18 was increased upon CFT073 infection, but the expression of the IL-18 receptor was reduced to basal levels." (PMID 35132157, 2022). "However, in patients, where Lepsey NLV1 was present along with LD, the level of IL-18 in serum was consistently and significantly reduced compared to only LD infection." (PMID 36002553, 2022). "Overall, BCG vaccination and IL-12+IL-18 treatment both promoted ILC1-like cells in early stages of infection, which could contribute to protection against Mtb at an early stage of infection." (PMID 35443177, 2022). "Treg IL-10 was upregulated during late infection, perhaps to combat the coincided inflammatory cytokines (IL-1, IL-18, and IL-6) high levels and intense pathological lesions, protect the host from excessive tissue damage, and contribute to the Th1/Th2 balance and immune homeostasis." (PMID 36187827, 2022). "IL-18 has been reported as a predictor of infection severity." (PMID 36111789, 2022). "In order to test whether SEZ would trigger the secretion of IL-1β and IL-18 in vivo, cytokine levels in PLF were measured by enzyme-linked immunosorbent assay (ELISA) after 24h-infection." (PMID 36311722, 2022). "Additionally, ASFV-Δ9L/Δ7R infection exhibited dramatic induction of genes important during the acute-phase response, such as IL-1A, IL-1B, IL-10, and IL-18, tumor necrosis factor alpha (TNF-α), and several members of the complement pathway (C1R)." (PMID 35867564, 2022). "It was reported that IL-22 could activate ILC3s indirectly by inducing epithelial IL-18 during infection and IL-25-expressing epithelial cells could suppress IL-22 production by ILC3s72,73." (PMID 34294718, 2021). "Interleukin-18 is thought to play a broad role in defence against infections." (PMID 34911594, 2021).